RPL29 (ribosomal protein L29)
Description:
Component of the large ribosomal subunit. The ribosome is a large ribonucleoprotein complex responsible for the synthesis of proteins in the cell.
Synonyms: HIP; HUMRPL29; L29; eL29; RPL29P10; RPL29_3_370
Tractability: Small molecule: an approved drug acts on it; a structure with a bound ligand is known; a high-quality ligand is known. PROTAC: ubiquitination databases record sites on it; its protein half-life has been measured; a small molecule that binds it is known. Other modalities: a drug acting on it is in phase 2 or 3 trials.
Gene: Protein-coding gene on chromosome 3 (51,993,522 to 51,995,953, reverse strand). Ensembl gene ENSG00000162244.
Subcellular location: Cytoplasm
Subcellular location (Human Protein Atlas): Cytosol; Endoplasmic reticulum; Nucleoli
Pathways (Reactome):
Metabolism of proteins: Eukaryotic Translation Termination; Formation of a pool of free 40S subunits; GTP hydrolysis and joining of the 60S ribosomal subunit; L13a-mediated translational silencing of Ceruloplasmin expression; PELO:HBS1L and ABCE1 dissociate a ribosome on a non-stop mRNA; Peptide chain elongation; Ribosome Quality Control (RQC) complex extracts and degrades nascent peptide; SRP-dependent cotranslational protein targeting to membrane; ZNF598 and the Ribosome-associated Quality Trigger (RQT) complex dissociate a ribosome stalled on a no-go mRNA
Metabolism of RNA: Major pathway of rRNA processing in the nucleolus and cytosol; Nonsense Mediated Decay (NMD) enhanced by the Exon Junction Complex (EJC); Nonsense Mediated Decay (NMD) independent of the Exon Junction Complex (EJC)
Cellular responses to stimuli: Response of EIF2AK4 (GCN2) to amino acid deficiency
Developmental Biology: Regulation of expression of SLITs and ROBOs
Disease: Viral mRNA Translation
Metabolism: Selenocysteine synthesis
Gene Ontology:
Molecular function: cadherin binding; RNA binding; structural constituent of ribosome; heparin binding
Biological process: cytoplasmic translation; embryo implantation; negative regulation of myoblast fusion; spermatogenesis; striated muscle contraction; translation
Cellular component: cytoplasm; cytosol; cytosolic large ribosomal subunit; cytosolic ribosome; endoplasmic reticulum; membrane; nucleolus; ribosome
Genetic constraint (gnomAD): Loss-of-function variants: 5 observed, 7.29 expected, observed/expected ratio (o/e) 0.69, 90% interval 0.36 to 1.43. That is too few expected variants to judge how well the gene tolerates losing a copy. Missense variants: 148 observed, 195.68 expected, observed/expected ratio (o/e) 0.76, 90% interval 0.66 to 0.87. Synonymous variants: 73 observed, 69.79 expected, observed/expected ratio (o/e) 1.05, 90% interval 0.87 to 1.27.
Homologues: Orthologues: chimpanzee RPL29 (97% identical), rabbit RPL29 (86% identical), guinea pig RPL29 (84% identical), rat Rpl29 (80% identical), mouse Rpl29 (79% identical), rat AABR07043813.1 (79% identical), rat AABR07068694.1 (79% identical), rat LOC120093247 (79% identical), rat LOC120095889 (77% identical), mouse Rpl27rt (76% identical), rat Rps29-ps20 (75% identical), dog RPL29 (75% identical), and 7 more.
Diseases named in the same sentence as RPL29 in open-access papers:
RPL29 is named in the same sentence as 29 diseases in open-access papers, as found by Europe PMC text mining. Sharing a sentence is not in itself a finding about the gene and the disease. The quoted sentences say what the papers report.
pancreatic cancer (8 papers, 2018 to 2025). "Inhibition of RPL26 and RPL29 in these cells is associated with reduced proliferation, increased apoptosis and blockage of cell cycle, which shed light on the importance of targeting these RPs as a potential therapy of pancreatic cancer." (PMID 34873618, 2021). "The knockdown of RPL26 and RPL29 expression ablates the proliferation of human pancreatic cancer PANC-1 cells." (PMID 35050240, 2022). "The depletion of RPL29 results in suppression of cell proliferation, induced cell cycle arrest at G0/G1 phase and enhanced cell apoptosis in pancreatic cancer cell." (PMID 33004906, 2020). "For example, we have reported that AAb against cellular ribosomal protein L29 could be detected in the serum of patients with pancreatic cancer." (PMID 39559295, 2024). "have discovered that the use of serum anti-RPL29 antibody retards pancreatic cancer cells proliferation in vitro suggesting that serum anti-RPL29 could be a biomarker in this cancer." (PMID 34873618, 2021). "The presence of anti-60S ribosomal protein L29 (RPL29) antibody in human serum was shown to inhibit the proliferation of pancreatic cancer cells in various cancers and is believed to be a novel candidate for a prognostic marker for unrespectable pancreatic cancer." (PMID 33472578, 2021). "By contrast, lower expression of RPL29, the one belongs to the NDP, is predicted to have a poorer outcome of unresectable pancreatic cancer, providing further evidence that RPL29 might be anti-tumorigenic." (PMID 34136404, 2021).
colon cancer (5 papers, 2010 to 2025). "RPL29 is up-regulated in colon cancer cells which correlates with the inhibition of apoptosis and promotion of the survival of the cancerous cells." (PMID 34873618, 2021). "For example, decreased levels of RPL29 induced differentiation of LS174T colon cancer cells with increased expression of two known markers of differentiation, galectin-4 and mucin-2." (PMID 20221446, 2010). "RPL29, an important protein in protein synthesis, was upregulated in colon cancer cells." (PMID 32282333, 2020). "Moreover, RPL29 binds and interacts with the extracellular matrix and knockdown of RPL29 has been reported to induce colon cancer cell differentiation." (PMID 29464047, 2018).
head and neck squamous cell carcinoma (2 papers, 2023). A squamous cell carcinoma that arises from any of the following anatomic sites: lip and oral cavity, nasal cavity, paranasal sinuses, pharynx, larynx, and salivary glands. "Finally, to determine whether 5′UTR isoform switches could also play a role in human cancer, we assessed RPL21 and RPL29 levels in 519 human head and neck squamous cell carcinoma (HNSCC) patients." (PMID 36550360, 2023).
laryngeal carcinoma (2 papers, 2016 to 2023). Carcinoma that arises from the laryngeal epithelium. "We suggest that the combination of ALAS1+RPL29 reference genes is best for normalization of target gene expression in laryngeal cancer and/or normal tissue samples." (PMID 38031942, 2023). "In the tissue group, PPIA and RPL29 had the lowest M-values, followed by HPRT1, which suggests that these same genes are the most stable internal reference genes for the study of human laryngeal cancer tissues." (PMID 27957397, 2016). "According to the results of geNorm, in the cell line + tissue group, RPL29 and HPRT1 had the lowest M-values, followed by PPIA, suggesting that these are the most stable internal reference genes for the study of human laryngeal cancer cell lines and tissues." (PMID 27957397, 2016).
squamous cell carcinoma (2 papers, 2023 to 2025). A carcinoma arising from squamous epithelial cells. "The downregulation of RPL29 can reduce the proliferation and invasion of squamous cell carcinomas." (PMID 41386760, 2025).
COVID-19 (1 paper, 2022). A disease caused by infection with severe acute respiratory syndrome coronavirus 2. "60S Ribosomal protein L29 (RPL29) was a highly expressed gene among all COVID-19 infected groups." (PMID 35983322, 2022). "Our findings also revealed that 60S Ribosomal L29 (RPL29) is a highly expressed gene in all COVID-19 infected groups, regardless of illness severity stage, implying a novel host receptor." (PMID 35983322, 2022).
glioma (1 paper, 2025). A benign or malignant brain and spinal cord tumor that arises from glial cells (astrocytes, oligodendrocytes, ependymal cells). "Besides LCP1, other 16 LRGs such as LGALS1 and RPL29 should be validated in glioma progression in future studies This study has several limitations that should be acknowledged." (PMID 40740857, 2025).
leukemia (1 paper, 2025). A malignant (clonal) hematologic disorder, involving hematopoietic stem cells and characterized by the presence of primitive or atypical myeloid or lymphoid cells in the bone marrow and the blood. "Flow cytometry analysis showed that knockdown of Rpl29 significantly decreased the leukemia burden and eliminated LSPCs in BM and spleen of secondary CML mice." (PMID 39668478, 2025). "Rpl29 knockdown eliminated LSCs and extended the survival of CML mice while Rpl29 overexpression accelerated leukemia development." (PMID 39668478, 2025). "The results showed significantly decreased enrichment of PRMT1 and H4R3me2a at the gene promoter region of Rpl29 in leukemia cells from the Prmt1 KO versus WT CML mice." (PMID 39668478, 2025). "Consistently, flow cytometry analysis showed that restoration of Rpl29 rescued the Prmt1 deletion‐mediated reductions of the leukemia burden and proportions of LSPCs in secondary CML mice." (PMID 39668478, 2025). "The successful overexpression of RPL29 in splenic leukemia cells from secondary CML mice was confirmed by Western blotting analysis." (PMID 39668478, 2025). "RPL29 knockdown in splenic leukemia cells was confirmed by Western blotting analysis." (PMID 39668478, 2025). "The results demonstrated that overexpression of Rpl29 shortened survival (median survival: Vector vs Rpl29 was 29 vs 18 days), worsened the splenomegaly and spleen weight, and increased the leukemia burden as well as the percentages of LSPCs in BM and spleen of secondary CML mice." (PMID 39668478, 2025). "RPL29 overexpression in splenic leukemia cells was confirmed by Western blotting analysis." (PMID 39668478, 2025).
liver cancer (1 paper, 2021). An epithelial or non-epithelial malignant neoplasm that arises from the liver. "Moreover, both NMT1 and AHSG were associated with the tumor stage, while RPL29 reversely correlated with the tumor stage in liver cancer." (PMID 34136404, 2021). "Trough statistical analysis in 301 liver cancer specimens showed a positive relationship between AHSG and NMT1, whereas a negative relationship between RPL29 and NMT1 were revealed, further demonstrating that NMT1 might oppositely regulate expression of NUP and NDP." (PMID 34136404, 2021).
melanoma (1 paper, 2025). A malignant, usually aggressive tumor composed of atypical, neoplastic melanocytes. "BRAF V600K melanomas were downregulated for module 1 (RPS15, RPL29, RPL10)." (PMID 39796775, 2025).
metastatic cancer (1 paper, 2021). A carcinoma which has spread from the original site of growth to another anatomic site. "Although Rpl29 and Rpl13a were downregulated in cancer cells of mouse models compared to normal mammary epithelial cells, these two genes were significantly upregulated in metastatic cancer cells compared to primary cancer cells." (PMID 34497807, 2021).
ovarian tumor (1 paper, 2020). "In the library prepared from ovarian tumor tissue, 5 clones with coding sequences were identified using the HMGB1 bait (C1QA, DAG1, RPL29, RSF1, TGM2), and 6 (COMMD1, MIEN1, PCBP1, TBC1D25, ZFR, ZNF428) were identified with the HMGB2 bait." (PMID 32867128, 2020).
promyelocytic leukemia (1 paper, 2019). "Thus, the top two AML genes, MPO (myeloperoxidase) and PML (promyelocytic leukemia) have the GCHs 22.96 and 21.95, below those of the 56th and the 59th ranked ribosomal proteins RPL29 (23.64) and RPL13 (22.12)." (PMID 31349573, 2019).
Shwachman-Diamond syndrome (1 paper, 2018). "Gene expression profiles of bone marrow mononuclear cells from patients with Shwachman-Diamond syndrome revealed significant downregulation of RP genes, including RPS9, RPS20, RPL6, RPL15, RPL23, and RPL29, or upregulation of RPS27." (PMID 29954325, 2018).
stomach cancer (1 paper, 2010). "Taking these findings together, B2M seems to be the most suitable single reference gene for 'stomach cancer cell lines' and RPL29 for 'all stomach tissues'." (PMID 20507635, 2010). "RPL29 is also the best for comparing target gene expressions in stomach cancer cells and tissues." (PMID 20507635, 2010). "Actually, only RPL29 showed consistent expression range for all stomach cancer cells and tissues, suggesting that using single reference gene may be more appropriate for comparisons." (PMID 20507635, 2010). "This study validated RPL29 and RPL29-B2M as the best single reference genes and combination, for RT-qPCR analysis of 'all stomach tissues', and B2M and B2M-GAPDH as the best single reference gene and combination, for 'stomach cancer cell lines'." (PMID 20507635, 2010).
cancer (12 papers, 2010 to 2025). A tumor composed of atypical neoplastic, often pleomorphic cells that invade other tissues. "Expression of RPL29 was also reported to be associated with cancer drug resistance." (PMID 35664774, 2022). "Genetic mutations and aberrant expression of the RPs (such as RPS23, RPS27, RPL29, and RPL35) have been linked to various cancers." (PMID 39410048, 2024). "RPL29 was identified as an oncoprotein because of its ability to promote cancer cell proliferation, to promote tumor angiogenesis, and to inhibit cell differentiation." (PMID 35664774, 2022). "Various translation regulators such as eIF4B, ABCE1 and 4E-BP1, or ribosomal proteins, for example RPL29 or RPL9 which have been linked to malignant PCa and other cancers, were found in low abundance in VCaPER." (PMID 36348939, 2022). "On the contrary, percentages of Rpl29-expressing and Rpl13a-expressing cells were notably decreased in cancer models." (PMID 34497807, 2021). "In comparison, in this study, the average expression levels of GAPDH and RPL29 were similar in stomach tissues and cancer cell lines." (PMID 20507635, 2010). "We examined, in addition to ACTB and GAPDH, four other reference genes, HPRT1, RPL29, 18S rRNA, and B2M that have been evaluated as reference genes in recent studies for other human cancers." (PMID 20507635, 2010). "Furthermore, the expression of RPL29, one of the key RPs overexpressed in various cancer types, was also downregulated by honey in PanCa cells." (PMID 39410048, 2024). "Notably, two function-unidentified ribosome protein genes, Rpl13a and Rpl29, were significantly downregulated in cancer cells." (PMID 34497807, 2021). "Notably, the RPL29 and MBP fragment peptides 135–149 and 168–177, respectively, are listed in SPENCER as tumor-specific for various cancers, suggesting their potential as novel neoantigens for immunotherapeutic strategies." (PMID 40649831, 2025).
tumor (7 papers, 2010 to 2025). "In our study, the expression stability of five reference genes ACTB, ALAS1, GUSB, HMBS, and RPL29 were investigated to determine the CRM1 gene expression profile in tumor tissues and normal tissues by NormFinder analysis." (PMID 38031942, 2023). "HPRT1, B2M, and RPL29 in tumor stomach tissues passed the normality in DAP- and SW-tests." (PMID 20507635, 2010). "The most downregulated protein (RPL29, log2FC –5.2), is a member of the 60S ribosome which indicates that C3 may be acting to modify translational pathways, consistent with a hypothesis that C3 is exerting anti-tumor effects through 37 LR." (PMID 29464047, 2018). "Some scientists reported that tumor angiogenesis is enhanced in mice lacking β3-integrins whereas RPL29 is significantly upregulated in β3-null endothelial cells and regulates angiogenesis via controlling VEGF47." (PMID 33004906, 2020). "Significant expression increase from normal to tumor stomach tissues (p < 0.05) were observed in HPRT1 (p = 0.011) and 18S rRNA (p = 0.021), but not in ACTB (p = 0.058), GAPDH (p = 0.918), B2M (p = 0.740), or RPL29 (p = 0.208)." (PMID 20507635, 2010). "In case of normalization by RPL29 which was predicted as most stable single reference gene in NormFinder and most stable combination with HPRT1 in geNorm, the high-low pattern of RQ difference between normal and tumor was similar to RQ by HPRT1 though there were difference in three patients." (PMID 20507635, 2010). "RQ by RPL29 (T/N = 2.23×, p = 0.071), HPRT1 (T/N = 1.34×, p = 0.258), ACTB (T/N = 1.60×, p = 0.395), 18S rRNA (T/N = 1.36×, p = 0.527) and RPL29-HPRT1 (T/N = 1.76×, p = 0.086) also showed increasing GPNMB expression in tumor stomach tissues but it was not statistically significant." (PMID 20507635, 2010).
infection (1 paper, 2021). The state of being infected such as from the introduction of a foreign agent such as serum, vaccine, antigenic substance or organism. "Among the ribosomal proteins, Treacle ribosome biogenesis factor 1(TCOF1), nuclear transport factor 2 like export factor 2(NXT2), ribosomal protein L37(RPL37), ribosomal protein L29 (RPL29) and mitochondrial ribosomal protein S18A(MRPS18A) are all up-regulated in the early stages of infection." (PMID 34092256, 2021).
RPL29 also shares sentences with these, for which no sentence is quoted: Anxiety (2 papers); depression (2); osteoarthritis (2); atherosclerosis (1); hypothyroidism (1); lung carcinoma (1); metastatic melanoma (1); osteoporosis (1); ovarian carcinoma (1); Splenomegaly (1); viral infection (1).